JAK2 (Janus kinase 2)
Diseases named in the same sentence as JAK2 in open-access papers (continued):
Sharing a sentence is not in itself a finding about the gene and the disease.
cancer (continued). "The canonical pathways module of IPA revealed that these up-regulated genes participate in pathways related to cancer, hypoxia, AMPK, PI3K and JAK2 signaling." (PMID 29137349, 2017). "A variety of downstream signaling cascades can be triggered by nicotine through α7 nicotinic receptors, including the Ras/Raf-1/MEK1/ERK and JAK-2/STAT-3 pathways, resulting in the progression of cancer." (PMID 28974241, 2017). "Blockade of TGF-β as well as JAK2/STAT3 signaling reduced the proliferation and cytokine production of both cancer cells and MFs in culture." (PMID 28819126, 2017). "Recent studies reported that CXCR4 induced cancer cell migration and invasion by activating AKT, ERK, Jak2, and Stat3." (PMID 29069741, 2017). "We show that activation of JAK2/STAT signaling occurs in mast cells, macrophages and cancer cell during allergic inflammation." (PMID 28968979, 2017). "Using knockout and a chemical inhibitor, our data show that JAK2 was necessary for IFNγ-induced IRF1 and cancer cell surface expression of HLA-ABC MHC class I molecules." (PMID 28977839, 2017). "Due to the role of STAT3 in tumorigenesis and the abnormal activation of the pathway in several cancer types including GBM, the JAK2/STAT3 pathway has attracted considerable attention as a potential novel therapeutic target." (PMID 29253028, 2017). "Overexpression of constitutively active STAT3 partly reversed the anti cancer effects of (−)-oleocanthal, which inhibited STAT3 activation by decreasing the activities of JAK1 and JAK2 and increasing the activity of SHP-1." (PMID 27259268, 2016). "Statins are known to reduce cell proliferation via down-regulation of critical signaling pathways in a few human cancers, including AKT/mTOR, MAPK, JAK2/STAT3, Ras, NF-κB, JUNK and RhoA/ROCK pathways." (PMID 26503475, 2016). "Previously, miR-375 was found to be significantly down-regulated in various types of cancers, suppressing core hallmarks of cancer by targeting several important oncogenes, such as PDK1, JAK2, AEG-1." (PMID 27036030, 2016). "Microtubule inhibitors have been shown to inhibit Janus kinase 2/signal transducer and activator of transcription 3 (JAK2/STAT3) signal transduction pathway in various cancer cells." (PMID 27367272, 2016). "For example, natural products inhibit JAK2/STAT3 signaling and induce apoptosis in various cancer cells." (PMID 26755649, 2016). "In a subsequent study, we also added AG490 (a specific inhibitor of Jak2, 100 μM), LY294002 (a specific inhibitor of PI3K, 100 μM), or both AG490 and LY294002 to the B7-H3-overexpressing SW480-B7-H3 cancer cells." (PMID 27145365, 2016). "Recently, many studies has shown several mechanisms associated with rapamycin resistance, which including promyelocytic leukemia (PML) gene, JAK2/STAT5, Notch1 and MAPK mediated resistance to mTOR-targeted therapies in cancer." (PMID 26872016, 2016). "Treatment with peptide 520 suppressed JAK2, phospho-STAT3, and Bcl-xL, resulting in cancer cell death." (PMID 27409672, 2016). "In the Cancer Signaling Phospho Antibody Microarray PCS248 analysis of COL6A1 silencing, the JAK2-STATs pathway was the most significantly changed." (PMID 25895032, 2015). "Some of them, such as UBE2C, CASP3, CCND1/2, STAT3, JAK2 and MMP-9, have been used as markers of cancer malignancy." (PMID 26603105, 2015). "We discuss two cases of hubs that are strongly involved in cancer: BRAF and JAK2, both with phenotypic pathogenic mutations occurring in ordered regions and affecting the disorder content of distal sites in the domain." (PMID 26322316, 2015). "The protein levels of phosphorylated JAK2 and STAT3 in cancer cells were increased upon co-culture with ADSCs." (PMID 25797257, 2015).
cancer (continued). "Btk silencing effectively reduced the expression of the Janus kinase 2 (JAK2)/STAT3 pathway, which in turn suppressed the survival of cancer cells through Sox-2 and BCL-XL genes and, finally, restored responsiveness to cisplatin." (PMID 26036311, 2015). "Cancer cell line HCT116 was treated with trametinib (5μM) alone, or in combination with one of the following agents: ruxolitinib (2.5μM, JAK2 inhibitor), tofacitinib (2.5μM, JAK3 inhibitor) or KX2-391 (2.5μM, Src inhibitor)." (PMID 25961376, 2015). "JAK2/STAT3 is one of the major signaling pathways triggered by IL-6 and is constitutively activated in numerous cancer cell lines and types, including GC tissues." (PMID 24527098, 2014). "In fact, several drugs targeting this pathway are in development or used in the clinic for the treatment of cancer including neutralizing anti-IL-6 antibodies and small molecule or peptide inhibitors of STAT3 and/or JAK2." (PMID 24657910, 2014). "Except for AZD1480 which is a JAK2 inhibitor currently in clinical trials, the rest are FDA-approved anti-cancer drugs." (PMID 25036984, 2014). "The JAK2/STAT3 pathway is critical for cytokine and growth factor-mediated responses regulating EMT biology in fibrogenesis and cancer." (PMID 25405202, 2014). "Mechanistic characterization revealed that NSC-743380 suppressed the phosphorylation of C-terminal domain of RNA polymerase II, induced JNK activation, inhibited JAK2/STAT3 phosphorylation and suppressed cyclin D1 expression in sensitive human cancer cells." (PMID 22174819, 2011). "FLLL32 was also more potent than four previously reported JAK2 and STAT3 inhibitors as well as curcumin to inhibit cell viability in these cancer cells." (PMID 20712901, 2010). "Since the p38 MAPK and JAK2/STAT3 signaling pathways are known to be upstream regulators of COX-2 in cancer cells, the activation of the ERK/MAPK and JAK2/STAT3 pathways by COX-2 may form a positive feedback loop to promote the survival of NPC cells." (PMID 41293174, 2025). "In addition, EZH2 can likewise take part in various molecular signaling pathways, like PI3K/Akt/mTOR and JAK2/STAT3, to promote the proliferation and migration of cancer cells." (PMID 41154714, 2025). "4HGE, a crystal structure of the JAK2 tyrosine kinase (JH1 domain) in complex with the small molecule inhibitor compound 8, providing insights into selective kinase inhibition pertinent to cancer and inflammatory disease therapies." (PMID 40795814, 2025). "Results showed that DHA effectively suppresses cancer stem cell‐like properties and significantly inhibits invasion and migration by regulating the JAK2/STAT3 signaling pathway and reducing the phosphorylation of JAK2 and STAT3." (PMID 41231037, 2025). "Additionally, MCPIP1 inhibits cancer stemness and mixed EMT of PC cells by suppressing the IL6/JAK2/STAT3 axis." (PMID 40874680, 2025). "Secondly, while we demonstrated that Lyc.HCL inhibits cancer cell growth, metastasis, and invasiveness by targeting TRIM22 and modulating the JAK2/STAT3 and ERK pathways in vitro and in vivo, our in vivo experiments were limited to a subcutaneous xenograft model." (PMID 40075566, 2025). "The IL6/JAK2/STAT3 pathway is key to tumorigenesis, progression, metastasis, and immune escape, and the transcription factor STAT3 controls how quickly cells grow, move, and spread in a number of different types of cancer." (PMID 40874680, 2025). "By targeting TRIM22 and modulating the JAK2/STAT3 and ERK signaling pathways, Lyc.HCL may offer a promising strategy for the treatment of ESCC and other cancers in which TRIM22 plays a significant role." (PMID 40075566, 2025).
cancer (continued). "Previously published researches have demonstrated that CXCR4 was overexpressed in GC and affects the proliferation, migration and invasion of cancer cells via the activation of diverse signaling pathways, such as ERK/Akt, NF-kB, JAK2/STAT3, and Wnt/β-catenin pathways." (PMID 38402299, 2024). "Likewise, TAMs conditioned by CRC notably elevate IL-6 secretion, activating the Jak2/STAT3 pathway and indirectly boosting forkhead box Q1 (FoxQ1) expression in cancer, thus reinforcing EMT and cancer stem cell attributes." (PMID 39286635, 2024). "The regulation and inhibition of the IL-6/JAK2/STAT3 pathway is conducive to cancer prevention and treatment as well as improved prognosis and, therefore, represents an important target for designing anti-cancer drugs." (PMID 38715108, 2024). "The JAK2/STAT3 hyperactivity results in the onset and development of cancer." (PMID 38706884, 2024). "C3 can also activate the JAK2/STAT3 signalling pathway, that is hypothesized to lead to poorer cancer outcomes." (PMID 38902713, 2024). "ROS play a role in cancer suppression, but it has been shown that autophagy promotes tumor angiogenesis by activating the JAK2/STAT3 pathway and targeting VEGF; in addition, autophagy regulates the ability of cancer stem cells (CSCs) to differentiate into TECs." (PMID 38824197, 2024). "While the benefit of smoking cessation is widespread across cancer prevention, the mechanistic implications of the present study for patients with known TET2 or JAK2 V617F CHIP may be potentially meaningful." (PMID 37601662, 2023). "BTK silencing significantly decreased the expression of the Janus kinase 2 (JAK2)/signal transducer and activator of transcription 3 (STAT3) and, in consequence, reduced cancer cell viability via the SRY-box transcription factor 2 (Sox-2) and BCL-XL genes and increased susceptibility to cisplatin." (PMID 36903645, 2023). "In this model, we have observed a transcriptional alteration of genes participating in processes that have a role in cancer and MPNs, revealing that these processes can be directly perturbed by mutant calreticulin without JAK2 or MPL intervention in the worm." (PMID 36611979, 2023). "In fact, an animal model of PRL-induced breast carcinogenesis demonstrated that JAK2 is needed for cancer initiation but not for maintenance of tumors." (PMID 37834225, 2023). "While triptolide could down-regulate PD-L1 expression in cancer cells by inhibiting Jak2/STAT1 pathway, which helped to inhibit tumor growth and metastasis in cancer treatment." (PMID 37497002, 2023). "This would be consistent with the demonstrated NOT-elicited inhibition of JAK2 activation, and the documented roles of JAK2/STAT3 signaling in oncogenicity, maintenance of cancer stemness, cellular survival under stress, and resistance to multiple anticancer therapies." (PMID 37299411, 2023). "Evidently, there are other ongoing investigations exploring diversely capped HDAC-6 inhibitors for multi-target (e.g., Janus kinase 2 or JAK2 and heat shock protein 90 or Hsp90) activities as potential synergistic pharmacotherapeutic agents for disparate diseases (e.g., fungal and cancer)." (PMID 37894975, 2023). "Silencing of miR-218-5p inhibited activation of the JAK2/STAT3 pathway by targeting KLF9, while KLF4, which belongs to the same family, could inhibit the JAK2/STAT3 pathway, which in turn affects cancer cell development." (PMID 37465460, 2023). "In addition, several signaling pathways, including MAPK/JNK and JAK2/STAT3, for SK1 in cancer have been described." (PMID 36500220, 2022). "As a result, quercetin’s anti-inflammatory and anti-apoptotic properties play an important role in cancer prevention by modulating the TLR-2 (toll-like receptor-2) and JAK-2/STAT-3 pathways and significantly inhibiting STAT-3 tyrosine phosphorylation within the inflammatory cells." (PMID 36233051, 2022).
cancer (continued). "Interestingly, it was reported that the activated IL-6/JAK2/STAT3 pathway can inhibit bax/bcl2 related caspase-dependent apoptosis, leading to the promotion of proliferation and metastasis of cancer cells." (PMID 36431925, 2022). "Among them, IL-6/janus kinase 2 (JAK2)/signal transducer and activator of transcription 3 (STAT3) signaling pathways may play a key role in the development of malignant tumors, participating in the entire process of invasion and metastasis." (PMID 36591515, 2022). "It has been claimed that myeloid-derived suppressor cells (MDSCs), which are precursors of DCs, macrophages, or granulocytes, have the ability to negatively regulate the immune response in cancer, with a subpopulation of monocytic MDSCs mediated by the EPOR-mediated Jak2/GATA3/STAT3 pathway induced." (PMID 35359375, 2022). "Janus kinase 2 (JAK2), phosphoinositide 3-kinase inhibitors/protein kinase B (PI3K/Akt) and extracellular related signal kinases (ERK) signaling was inhibited in pancreatic and liver cancer." (PMID 33544704, 2021). "Taken together, our study provides the impetus to discover new strategies, for instance, the development of efficient agents, including JAK2/STAT3 inhibitors and humanized monoclonal antibodies against IL6 to re-sensitize resistant NPC cells or other cancers that were resistant to chemotherapy." (PMID 34094941, 2021). "Of note, three orally active JAK2 inhibitors, ruxolitinib, baricitinib, and fedratinib, have been approved by the FDA for rheumatoid arthritis and myelofibrosis; they are being evaluated for human cancers in numerous clinical trials." (PMID 34066153, 2021). "The IL-6/JAK2/STAT3 pathway plays a crucial role in the growth and development of many cancers." (PMID 34277446, 2021). "This way, the inhibitory effect of SOCS3 on JAK2 is annulled, and the subsequent activation of JAK2/STAT3 signaling enhances cancer cell growth and migration; interestingly, activated STAT3 binds to the promoter of circ-SOD2 and further promotes its expression through a positive feedback loop." (PMID 34205978, 2021). "The consequence revealed that the high- and low- METAscore groups exhibited distinct mutation characteristics and the genes with a high mutation frequency in TTN, MUC4, PIK3CA, and MUC16 which all correlated with EMT and critical cancer pathways including PI3K/AKT and JAK2/STAT3 in CESC." (PMID 34277697, 2021). "Furthermore, JAK2/STAT3 signaling pathway involved in regulating the proliferation and apoptosis in a variety of cancer cells." (PMID 33995073, 2021). "Interestingly, alterations in JAK2, MYD88 and NPM1 genes, already have drugs FDA approved for other cancers." (PMID 33668731, 2021). "JAK2 functions as a prototypical kinase that phosphorylates STAT3, which activates the JAK2/STAT3 signaling pathway and promotes tumorigenesis and progression in several cancer types." (PMID 34496932, 2021). "In this cancer model, SIRT6 restoration led to apoptosis through upregulation of Bax and cleaved caspase-8, along with downregulation of Bcl-2 and inhibition of the JAK2/STAT3 pathway." (PMID 33800266, 2021). "In this work, we investigate (i) unexplored structure of the STAT-JAK2-Bcl-2-BAX signalling pathways, (ii) how changes in IFN-β, STATs and JAK2 affect cancer progression, (iii) development of optimized treatment scheme in a polymedicine approach (IFN−β+JAK2 inhibitor)." (PMID 34631119, 2021). "In the pathogenesis of cancer, elevated IL‐6 and IL‐27 could stimulate the activation of JAK1 and JAK2 enzymes, which subsequently mediate tyrosine phosphorylation of STAT3 at Tyr705." (PMID 33277798, 2021). "Results show that the level of LEPROT was consistently positively correlated with that of JAK1, JAK2, and STAT3, which suggested that JAK1/2/STAT3 might be the downstream LEPROT and mediate cancer cell proliferation and TME alterations." (PMID 34804118, 2021).
cancer (continued). "Importantly, JAK2 directly phosphorylates BECN1 at Y333, leading to an enhanced BECN1-VPS34 interaction and autophagy, a mechanism by which IL-6 regulates cancer chemotherapy resistance." (PMID 34131122, 2021). "Interestingly, a previous study showed that when JAK2/STAT3 signaling pathway is activated, cancer cells tend to escape the immune surveillance and metastasize to distant organs through blood circulation, resulting in the formation of metastatic lesions." (PMID 34895038, 2021). "Most known cancer genes have been found through primary cytogenetic analyses, although sequencing of cancer genomes has revealed new cancer genes including BRAF, EGFR, ERBB2, PIK3CA, PPP2R1A, and JAK2." (PMID 34298667, 2021). "The results indicate that ARL4C could be a “switch” between the EGFR path and the JAK2/STAT5/β-catenin path to maintain the proliferation, migration, and invasion of cancer cells when cells are exposed to Erlotinib and EGFR path is blocked." (PMID 33194732, 2020). "Our data supported that the downregulation of ARL4C upregulated β-catenin via activation of JAK2/STAT5, which could help the EGFR-path-blocked cancer cells to regain their malignant behaviors." (PMID 33194732, 2020). "In a recent study, cucurbitacin I (CUI) has been identified as a strong inhibitor of the JAK2/STAT3 signaling pathway (a common oncogenic signaling pathway), which is constitutively activated in many types of cancer; hence, it is considered as a milestone in cancer therapy." (PMID 32034276, 2020). "Furthermore, JAK2/STAT3 inactivation by ALK4 and FRK results in reduced cell survival and aggressiveness of different types of cancer." (PMID 31952344, 2020). "Collectively, these findings indicate that the inhibitory effect of IST5 on Stat5 phosphorylation in cancer cells is not due to inhibition of Jak2 or other key kinases including Jak1, Jak3, Tyk2, Src, Lck, Fyn, TrkB/C, Abl1 or Abl2." (PMID 33217941, 2020). "Since STAT5 activation in the various cancers is dependent on the phosphorylation by various tyrosine kinases, for example JAK2, Bcr-Abl, Flt3 and Src, targeting the tyrosine kinases to inhibit the activation of STAT5 is a feasible way of treating cancers dependent on STAT5 signalling." (PMID 32872372, 2020). "Moreover, LINC00511 was found to interact with a variety of signaling pathways including JAK2/STAT3, Wnt/β-catenin, and PTEN/AKT/FOXO1, in the pathogenesis of cancers." (PMID 32698787, 2020). "Both the mRNA and protein levels of JAK2 and CCND2 were enhanced in cancer tissues compared to those in normal tissues, and a positive correlation was observed between CCND2 and JAK2 expression in patient tissues (coefficient r value of 0.57, with statistical significance, P < 0.001)." (PMID 31511084, 2019). "In addition to JAK2 activation, EGFR-mediated FAK phosphorylation (Y925) and activation also promote migration and invasion of cancer cells." (PMID 31215502, 2019). "Although aberrant activation of STAT3 or STAT5 has been reported in a variety of human cancers, determining the activation state of STAT3 or STAT5 may permit evaluating the clinical potential of JAK2 inhibitors." (PMID 30717771, 2019). "Moreover, we show that the loss of p-STAT3 is accompanied by a decrease in the levels of gp130 and p-JAK2, two upstream regulators of p-STAT3 activity in breast (MDA-MB-231) and lung (A549) cancer cells." (PMID 31491838, 2019). "Thus, we should consider what is the detailed relationship between JAK2, STAT3, and FOXO3 in cancer cells." (PMID 31540495, 2019). "Pervanadate, a pharmacologic phosphatase inhibitor, was used previously to validate the inhibitory effect of SHP-1 in STAT3-activated cancer In this study, pervanadate was used to investigate the role of SHP-1 in the dephosphorylation of JAK2/STAT3 and the anti-EMT effect of ATO." (PMID 29409467, 2018).